ALB (albumin)
Diseases named in the same sentence as ALB in open-access papers (continued):
Sharing a sentence is not in itself a finding about the gene and the disease.
infection (continued). "Protease cleaves several important proteins, such as albumin, casein, secretory components, and gelatin, and breaks immunoglobulins A and G, resulting in the facilitation of the spread of infection and suppression of the host defense." (PMID 34835458, 2021). "The serum levels of aspartate aminotransferase (AST) and alanine aminotransferase (ALT) increased after infection, while that of albumin (ALB) decreased, which was positively correlated with the degree of liver damage." (PMID 35071045, 2021). "Using in vitro and in vivo infection models and cellular and biophysical assays, albumin was found to modulate C. albicans pathogenicity by neutralizing the peptide toxin candidalysin via hydrophobic interactions." (PMID 34154403, 2021). "Our series with SARS-CoV-2 infected patients as a model of severe infection confirms these previous results and we found that albumin levels correlate with in-hospital mortality, and especially severe low levels stablished at ≤3 g/dL." (PMID 34768653, 2021). "The results of relative concentration of serum protein fraction (%) and albumin/globulin (A/G) ratio in normal dogs and dogs infected with Babesia canis, Ehrlichia canis, or Hepatozoon canis single infections (mean±SD)." (PMID 34566333, 2021). "Malnourished people exhibit weaker immunity, increased risks of infection, and delayed wound healing, as indicated by their reduced BMI, hemoglobin, and albumin index values." (PMID 34209633, 2021). "Several statistically significant relationships between subject descriptors (sex, infection status, serum albumin, and body surface area [BSA]) and rezafungin PK parameters were identified, but none were deemed clinically relevant." (PMID 34398673, 2021). "All infected animals treated with K-874A did not lose weight, but infected control animals treated with bovine serum albumin in phosphate-buffered saline (BSA/PBS) lost weight 3 days after the infection." (PMID 34648602, 2021). "An estimate of the globulin was used to evaluate the status of immunity against infection or the degree of health condition by estimating total protein and albumin." (PMID 33363353, 2020). "Serum albumin, which is a major Zn-carrier, is reduced in a host due to infection with the blood-sucking nematode H. contortus." (PMID 33255492, 2020). "In our experience with a high comorbidity population, we have employed albumin infusion in highly selected cases with low albumin, low prealbumin, and high inflammatory markers, usually following surgery or severe infection." (PMID 32188148, 2020). "Other possible biomarker of LF infection is the reversal of albumin-to-globulin ratio which can provide healthcare professionals with a clue as to the cause of the change in protein levels." (PMID 33312698, 2020). "Also, reduction of albumin in serum may suggest continued loss of albumin or infection." (PMID 32637701, 2020). "Recent clinical guidelines have recommended early postoperative enteral nutrition as a method of reducing major complications, such as infection and anastomotic leakage, postoperative ileus and albumin requirements compared to parenteral nutrition." (PMID 33109092, 2020). "Haptoglobin (Hp) is one of the most abundant APPs, second only to albumin and immunoglobins, and its serum levels can be upregulated up to 8-fold in response to infection." (PMID 32694142, 2020). "The concentration of serum albumin will be affected by the nutritional status and other factors, including infection, inflammatory response, and fluid retention status." (PMID 33149221, 2020). "can occur even during storage and transportation while the finding of contamination of egg contents points to the possible route of infection in the hen being a vertical process through the yolk or albumin." (PMID 33363350, 2020).
infection (continued). "Numerous studies have shown elevated serum globulin levels and decreased albumin to globulin (A/G) ratio in patients with infection and advanced malignancy, suggesting their important role in the immune and inflammatory system." (PMID 33028348, 2020). "After infection, albumin and glucose were significantly decreased, while blood phosphorus, lactate dehydrogenase, and CRP were significantly increased." (PMID 32722980, 2020). "The contents of total protein, albumin, and triglyceride were decreased after infection on 4 and 8 dpi (p < 0.05), but they were increased after pretreatment or treatment with “Shi Ying Zi” powder and positive drugs (p < 0.05)." (PMID 32846893, 2020). "Albumin decreased significantly while the sum of globulins and gamma-globulins alone increased significantly with increasing infection density." (PMID 32995005, 2020). "Twelve samples from each group were taken for the estimation of the total protein, albumin, and subsequently globulin to evaluate the status of infection or health conditions." (PMID 33363353, 2020). "In dogs with complicated form of infection significantly lower means were found in TP (P < 0.001), albumin (P < 0.05) and β2-globulins (P < 0.001)." (PMID 33144631, 2020). "Subgroup analysis showed that the association between increased albumin-corrected serum calcium level and heightened infection-related mortality was enhanced in patients with lower serum albumin level and in younger patients." (PMID 32286455, 2020). "We found that a history of preterm birth, hospitalization in the last six months, intra-abdominal source of infection, organ failure, low serum albumin, and high levels of C-reactive protein and lactate, were independent risk factors for 90-day mortality." (PMID 33267829, 2020). "A few studies have indicated that albumin is a nutritional and inflammatory marker that reflects the potential for infection or disease activity." (PMID 32891125, 2020). "Infection with S. japonicum caused elevation of serum ALT, AST, ALP, HA and PIIINP levels and reduction of ALB and GLOB levels, which was markedly suppressed by XCH." (PMID 32410640, 2020). "Total protein in the plasma decreased significantly (GLM: n = 60, SE = 0.005, t = −3.1, P = 0.01) with increasing infection density, as did the albumin to globulin ratio (GLM: n = 60, SE = 0.030, t = −5.4, P < 0.001)." (PMID 32995005, 2020). "Each combination of SOFA with risk factors (including prior hospitalization, intra-abdominal source of infection, C-reactive protein, and albumin) improved the predictive performance of the model to different degrees." (PMID 33267829, 2020). "Albumin, which is exclusively synthesized by the liver and reflects the physiological response to injury and infection, has been identified as an independent predictor of mortality in patients with Kp-BSI." (PMID 33267829, 2020). "Albumin is known as an acute phase marker with reduced levels in cases of infection and chronic inflammation." (PMID 33094574, 2020). "Experiments in mice have shown that infection with a lethal dose of S. pneumoniae D39 leads to increased albumin level in BAL due to the disruption of the alveolar barrier." (PMID 32481512, 2020). "As infection continues the ability of albumin to transport nutrients depends upon the extent of free albumin." (PMID 33088822, 2020). "Low serum albumin levels affect the body’s immune function, including barrier function, leukocyte phagocytosis, and complement function, resulting in prolonged infection time, anti-infective effects, and increased mortality." (PMID 32795259, 2020). "As infection continues and viral particles expand the ratio between bound and unbound virion-albumin increases until a crisis point is reached." (PMID 33088822, 2020). "Specifically, an increase in temperature significantly increased infection of ALB LI individuals [M (29/30) L (23/30) Fisher’s exact test P < .05]." (PMID 31894724, 2020).
infection (continued). "Predictors of severe infection were evaluated using clinical data including age, sex, serum creatinine level, serum albumin level, use of methylprednisolone pulse, and OC occurrence on the basis of previous reports." (PMID 31349802, 2019). "The final model for infection-related mortality comprises six factors: age, sex, serum albumin, serum creatinine, total cholesterol, and weekly renal Kt/V." (PMID 30893369, 2019). "A total of 588 adult patients undergoing LDLT were retrospectively investigated, after 22 were excluded because of signs of overt infection or history of ALB infusion." (PMID 31821367, 2019). "Recently, the CRP/albumin ratio has been established as an independent prognostic marker in patients with infection, malignancy, and critical illness." (PMID 31781024, 2019). "One hypothesis suggests that decreased albumin concentrations inhibit the activation of macrophages and the apoptosis of unregulated macrophages, impairing immune responses and making patients more susceptible to infection or inflammatory reactions after surgery." (PMID 31547129, 2019). "The laboratory results haven’t displayed a significant difference between infection and non-infection groups, except for the albumin level and total iron binding capacity (TIBC)." (PMID 31167651, 2019). "Poor coughing ability, smoking habit, the high change of WBC and blood glucose levels, and low change of serum ALB levels can be used to predict the occurrence of postoperative infections among patients who have undergone McKeown esophagogastrectomy." (PMID 31772939, 2019). "Albumin, a biomarker for nutrition state, was shown to be related to postoperative complications, such as surgical site infection, and to postoperative outcomes." (PMID 31547129, 2019). "Among these media, M10, a medium used to expand mouse hepatic progenitor cells, gave the highest yield of 2.7% (±0.3%) ALB+ cells at 15 days post-infection (dpi)." (PMID 31270412, 2019). "In fact, the CRP/albumin ratio has been shown as an independent prognostic marker in patients with infection, malignancy, and other diseases." (PMID 31781024, 2019). "A randomized controlled trial of albumin administration to reduce infections in ACLF has commenced recruitment." (PMID 30873165, 2019). "The reduction of ALB concentration (ratio of ALB concentration at 5 weeks post-infection to pre-infection ALB levels at 4 months after Hep transplantation) correlated with peripheral viral load (R2=0.77, P<0.05)." (PMID 29361613, 2018). "We therefore assessed vascular permeability by administering fluorescein isothiocyanate (FITC) conjugated to albumin protein intravenously 6 days post infection." (PMID 29434238, 2018). "BLd-H77 had no impact on human hepatocyte viability in mice as assessed by serum albumin concentration over the course of infection." (PMID 29505618, 2018). "In patients undergoing PD, serum albumin, hsCRP, and WBC were independent predictors of all-cause and infection-related mortalities (all P < 0.05)." (PMID 29494637, 2018). "Albumin To prevenT Infection in chronic liveR failurE stage 2 is a multicentre, open-label, interventional RCT." (PMID 30344180, 2018). "We found that in HIV-infected mice, post-infection concentration of ALB was reduced to a median value of 118.8 μg/ml (range 0–593 μg/ml) from a pre-infection median value of 461 μg/ml (range 389-1131) within the group." (PMID 29361613, 2018). "Our study also found that poor nutrition condition such as low serum albumin level, high coagulation state as high fibrinogen leval, and infection at early stage of GBS such as high white blood cell count, are also predictors of poorer prognosis." (PMID 32922875, 2018). "Therefore, we speculated that the PCT/albumin ratio was associated with the severity of infection." (PMID 29995751, 2018).
infection (continued). "Five weeks post-infection, we found a decreased concentration of human albumin (ALB) in the blood, which coincided with a reduced number of engrafted human Hep in the liver of dual reconstituted mice." (PMID 29361613, 2018). "Single factor analysis revealed that risk factors for complicated infection in patients with AAV included age, smoking, pulmonary involvement, hemoglobulin, albumin, SCr level, CD4 + T cell count, BVAS, and immunosuppressive therapy with MMF, CYC and TW." (PMID 29902982, 2018). "The CRP/albumin ratio has been extensively studied as an independent prognostic marker in patients with infection, malignancy, and other diseases." (PMID 30297655, 2018). "The Group 3 monkeys were also significantly protected from SHIV-C5 infection compared with the monkeys in Group 1 that were immunized with human serum albumin and received the CD4mc (P = 0.020, log-rank test)." (PMID 29915222, 2018). "There was, however, a significant location by infection effect on blood albumin at these two time points, with uninfected Lab mice exhibiting the lowest levels of blood albumin." (PMID 29518091, 2018). "Serum albumin, hsCRP, and WBC were independent predictors of all-cause, cardiovascular, and infection-related mortalities after adjusting confounding factors in the entire population (all P < 0.05)." (PMID 29494637, 2018). "It is known that serum albumin levels are decreased in the presence of inflammation and infection due to the disproportionate distribution of protein between the albumin and globulin compartments." (PMID 30065944, 2018). "At 24 h post infection, albumin levels in BAL fluid were significantly reduced in IL-36R-/- mice and IL-36γ-/- mice compared to WT mice." (PMID 29166668, 2017). "Serum albumin levels decrease during an inflammatory response to surgery or infection as the liver shifts its production toward acute phase proteins." (PMID 28622070, 2017). "Heterogeneity were found in the pooled MD of albumin and in the pooled RR for infection (P = 0.05, I2 = 61 % and P = 0.003, I2 = 68 %)." (PMID 28093079, 2017). "The funnel plots of pooled MD in albumin levels between the infection and non-infection groups and in the incidence of SSI in the two groups were both basically symmetrical, demonstrating no significant publication bias." (PMID 28093079, 2017). "In deep SSI subgroup, the infection rate was 0.61 % (17/2767) in the albumin <3.5 g/dL group and 0.18 % (108/58,818) in the albumin >3.5 g/dL group, (RR = 2.62, 95 % CI [1.56 4.42], Z = 3.62, p = 0.0003) in a fixed model (I2 = 0 %)." (PMID 28093079, 2017). "All three rhinoceroses showed significant increases in albumin between the pre- and post-infection periods, with a concurrent decrease in globulins." (PMID 28686714, 2017). "Brain albumin content was elevated in Masp2−/− (312.23 vs. 86.27 μg/mg tissue, P = 0.006) and WT (262.21 vs. 42.85 μg/mg tissue, P < 0.001) mice at 30 h after infection compared to saline-inoculated mice." (PMID 28086930, 2017). "The significantly decreased albumin indicated the liver protein synthesis was seriously impaired during the infection." (PMID 29137226, 2017). "WT mice and EP2-/- mice were treated intratracheally with 2.0 × 105 CFU P. aeruginosa, and then quantitated bacterial burden in BAL and spleen, the production of pro-inflammatory cytokines and albumin concentration in BAL at 24 h post infection." (PMID 29166668, 2017). "Following infection, heterophils decreased ALB and FN1, and released MMP9 to enable their translocation to the site of infection." (PMID 28623956, 2017). "In organ space SSI subgroup, the infection rate was 0.37 % (10/2688) in the albumin <3.5 g/dL group and 0.17 % (100/58,642) in the albumin >3.5 g/dL group, (RR = 2.17, 95 % CI [1.13 4.15], Z = 2.34, p = 0.02 in a fixed model (I2 = 18 %)." (PMID 28093079, 2017).
infection (continued). "A random effects model was applied for meta-analysis, and the results showed that preoperative albumin was significantly lower in the infection group than in the non-infection group (OR = −2.28, 95 % CI [−3.97, −0.58], P =0.008)." (PMID 28093079, 2017). "But long-lasting and significantly elevated serum levels of ALT and AST as well as low ALB levels were observed after infection, indicating liver injury." (PMID 28900143, 2017). "In this model, TBiL, albumin, HE, INR, blood neutrophils percentage count, and suspicion of infection were independent risk factors for death." (PMID 29312583, 2017). "In this study, the infection process of Zika virus (ZIKV) in Aedes aegypti was characterized by oral exposure via viral suspension meals within minimally bovine serum albumin complemented medium or within whole blood." (PMID 28796799, 2017). "Kuehn and Gaunt reported low albumin globulin ratio as serum biochemical abnormality in natural infection with E. canis." (PMID 28344412, 2017). "In superficial SSI subgroup, the infection rate was 1.64 % (45/2745) in the albumin <3.5 g/dL group and 0.67 % (392/58,721) in the albumin >3.5 g/dL group, (RR = 2.46, 95 % CI [1.81 3.35], Z = 5.73, p < 0.00001 in a fixed model (I2 = 0 %)." (PMID 28093079, 2017). "Both IM and IN infection induced a decrease in albumin and calcium levels, an increase in globulin, alkaline phosphatase, alanine aminotransferase, and amylase while maintaining a stable total level of protein." (PMID 28545034, 2017). "Of note, we found that low serum phosphate levels combined with being age 65 years or older or with dialysis vintage longer than one year or with a serum albumin level lower than 3.9 g/dL were related to a significantly increased infection-related mortality." (PMID 28973026, 2017). "The Dialysis Outcomes and Practice Patterns Study (DOPPS) reported that higher serum ALP levels were related with lower serum albumin levels and higher infection-related mortality in HD patients." (PMID 27310428, 2016). "Factors that were significantly associated with death from any infection included higher NRS-2002 scores, higher serum chromium levels and lower albumin levels." (PMID 26938553, 2016). "In contrast, hemoglobin, creatinine, and albumin levels significantly decreased by day 5 post-infection." (PMID 27855182, 2016). "Human serum albumin (HSA) was intravenously administered to measure the leakage of HSA from the circulation into the alveolar space at 24 hrs post infection (p.i.)." (PMID 27476670, 2016). "The analysis of the course of laboratory parameters in DOBV-Sochi infection demonstrated a prolonged phase with elevated levels of leukocytes and serum creatinine and decreased levels of thrombocytes and serum albumin compared to infection with PUUV." (PMID 27842513, 2016). "Albumin has been described to decrease as a part of the metabolic response to injury or infection despite nutritional status." (PMID 26961495, 2016). "The expression of four genes were significantly induced whereas one, albumin, was repressed by infection." (PMID 27197554, 2016). "After 20 months of conservative therapy, the patient lost 43 kg; despite two episodes of infection, albumin plasma levels increased up to 3.7 g per day." (PMID 26926587, 2016). "Patients with nPCR ≧ 1.2 g/kg/day combined with albumin <4 g/dL and nPCR <1.2 g/kg/day combined with Albumin <4 had higher CV and infection related mortality rate than patients with nPCR ≧ 1.2 g/kg/day combined with albumin >4 g/dL." (PMID 27752119, 2016). "The levels of serum-pepsinogen indicated a low infection level and the albumin values were in all cases within the range of healthy calves, although significant differences were found between groups." (PMID 27283323, 2016). "Albumin To prevenT Infection in chronic liveR failurE (ATTIRE) stage 1 is a multicentre, open label dose feasibility trial." (PMID 26810999, 2016).